BCR (BCR activator of RhoGEF and GTPase)
Diseases named in the same sentence as BCR in open-access papers (continued):
Sharing a sentence is not in itself a finding about the gene and the disease.
cancer (continued). "Secondly, as a cancer of B cell origin, analysis of the corresponding BCR library will allow us to determine clonal relationships between different cancerous B cells at different stages of differentiation." (PMID 38149239, 2023). "The analysis showed that our motifs derivedfrom BCR-ABL activity in yeast match specific activities that canbe profiled in phospho-proteomics measurement of human cancer cells." (PMID 37053475, 2023). "It has recently been demonstrated that the localization of breakpoints, particularly within the major BCR, has an impact on cancer biology and clinical behavior: breakpoints within KMT2A intron 11 are associated with poorer outcome." (PMID 37019990, 2023). "In CML, the constitutively active BCR::ABL1 kinase drives leukaemic proliferation through stimulation of several key cell survival pathways frequently activated in cancer." (PMID 37591854, 2023). "On the contrary, the anti-cancer effect of imatinib on K562 cells is originated from the decrease of p-BCR-ABL." (PMID 37215441, 2023). "As antigen-specific TCR and BCR were also an important feature of the immune system for recognizing pathogens and cancer cells." (PMID 35898926, 2022). "For example, in cancer, oncogenes of donor cells can be transformed into recipient cells by apoptotic bodies or the BCR/ABL hybrid gene in EVs, and then expressed on recipient cells." (PMID 34359729, 2021). "The relationships of glucose consumption to, on one hand, BCR/Abl-induced transformation and, on the other, glutamine metabolism in cancer cells emerged from a number of studies." (PMID 34503182, 2021). "There is no doubt that identifying targetable vulnerabilities at the core of a cancer’s oncogenicity has yielded remarkable and leaping advances in therapy as with the identification of the BCR-ABL fusion protein in CML and the development of Gleevec." (PMID 33803326, 2021). "In transgenic mice in which the expression of BCR-ABLp190, LMO2, and BCR-ABLp210 was restricted to HSCs via the Sca-1 promotor, carcinogenesis was initiated by the oncogenes, and the resultant cancer recapitulated lineage-restricted human disease." (PMID 31861691, 2019). "Recently, CD19 chimeric antigen receptor T-cell therapy (CAR-T) therapy, and Bi-specific T-cell engager (BiTE) therapies have shown promise in treating hematological malignancies that result from BCR fusion protein driven cancers." (PMID 31105873, 2019). "The commonality of BCR as a fusion partner will be addressed and the molecular mechanisms of these BCR fusions will be discussed in detail, along with current treatment options and patient outcomes for cancers positive for these fusions." (PMID 31105873, 2019). "The understanding of these BCR fusion protein induced stem cell cancers will give further insight for additional therapeutic advancements." (PMID 31105873, 2019). "Although BCR fusions have been detected in solid tumors, BCR fusion proteins that are drivers of cancer have solely been identified in hematological cancers to date." (PMID 31105873, 2019). "Based on the previously cited example in Belgium, this hybrid approach is possible today for cancer research using data from the BCR and IMA, both of which are provided with appropriate tools for collection, selection, and merging." (PMID 30906740, 2019). "In this and our previous study we use mouse models: in the previous study the disease was driven by the proto-oncogene BCR/ABL1, while in this study cancer risk was elevated by deletion of the tumor suppressor ARF." (PMID 29441205, 2018). "Over expressions of several abnormal/mutated growth factors (e.g., MYC, PI3K, MAPK, erythropoietin receptor-B cell factor-1-EBCR1 or BCR) that are also known to contribute to the multistep carcinogenesis in adult cancers are reported in childhood cancers." (PMID 27558401, 2016). "Nilotinib binds to and inhibits the kinase domain of ABL/BCR-ABL but also interacts with other cancer-expressed kinases including DDR1, KIT and PDGFR." (PMID 27556570, 2016).
cancer (continued). "These clusters are enriched in cancer-related pathways, such as BCR signalling, epidermal growth factor receptor (EGFR) signalling and extracellular signal-regulated kinase (ERK) signalling." (PMID 27982015, 2016). "We tested many cancer cell lines and found Bisindolylmaleimide IX in general showed a modest cytotoxic activity, with the exception of BCR-ABL positive cell lines." (PMID 27564101, 2016). "Aside from rare exceptions where we have a target specific to cancer, for example in the case of novel fusion proteins such as BCR-ABL, anything that induces apoptosis in cancer cells will also potentially induce apoptosis in healthy cells." (PMID 24595238, 2014). "Some types of cancers are characterized reliably by mutations in similar pathways or identical genetic alterations, such as the BCR-ABL translocation or RB mutation in retinoblastoma, but even these cancers can be highly diverse with regard to other mutations." (PMID 23396885, 2013). "A second pre-requisite for a candidate TAA is its expression at high level on cancer cells which reinforces interaction between BCR or TCR and the putative TAA." (PMID 23805414, 2013). "We previously found that TAPP2, in association with the F-actin-binding proteins utrophin and syntrophin, functions in the firm adhesion of BCR- or SDF-1-activated cancer B cells to extracellular matrix proteins." (PMID 23460911, 2013). "We show that many translocation-prone pairs of regions genome-wide, including the cancer translocation partners BCR-ABL and MYC-IGH, display elevated Hi-C contact frequencies in normal human cells." (PMID 23028501, 2012). "Classic examples of recurrent genomic rearrangements in cancer are the BCR-ABL translocation (observed in >90% of cases of chronic myeloid leukemia) and the MYC-IGH fusion (observed in ∼90% of cases of Burkitt's lymphoma)." (PMID 23028501, 2012). "CBL which is involved in cancer initiation and progression and is believed to form a multi-protein complex with BCR-ABL is a putative targets of miRs-31 and miR-155." (PMID 22511990, 2012). "The breakpoints of this translocation lie in two genes, BCR and ABL, and the translocation results in the BCR-ABL fusion gene that is directly implicated in the development of this cancer." (PMID 23300412, 2012). "This study was therefore undertaken to investigate the importance of functional BCR–ABL TK in determining the sensitivity of CML-derived cell lines to anti-cancer agents." (PMID 11986783, 2002). "The overall results confirmed the high potential of BCR-NLPs for cancer theranostic application." (PMID 42211385, 2026). "Notably, these recurrent SLRs were associated with genes known to be implicated in cancer, as evidenced by the Catalogue of Somatic Mutations in Cancer (COSMIC), including RALGDS, BCR, SH2B3, LMNA, and GATA2." (PMID 40193528, 2025). "BCR::ABL1-targeting TKIs represent a typical success of precision medicine in cancer treatment." (PMID 40447744, 2025). "The BCR gene is a key player in the pathogenesis of several cancers, including AML." (PMID 38902412, 2024). "In particular, NOTCH2 H107P and BCR T1127S variants were almost clonal (i.e., present in all somatic cells), whereas EPHA7 L564F and MTOR S920F were subclonal alterations, present in around 35% of cancer cells." (PMID 39421445, 2024). "Taken together, our results might indicate that TCR and BCR signaling pathways could serve essential roles in aging and cancer." (PMID 36672292, 2023). "Since cancer somatic mutations can generate neoantigens, an obvious upregulation of antigen presentation genes across all cancer cell clusters suggests clonal expansion of TCR or BCR to neoantigens." (PMID 36248860, 2022). "The co-occurrence of BCR::ABL1 kinase domain mutations and cancer gene mutations in a high proportion of resistant patients indicates that we should not consider resistance as either BCR::ABL1-dependent or BCR::ABL1-independent." (PMID 35158889, 2022).
cancer (continued). "Moreover, SEER database does not allow adjustment or specific analyses that focus on later cancer control endpoints such as, for example BCR rates." (PMID 36561531, 2022). "The immune-activated MPMs harbored the highest lymphocyte infiltration, growing TCR and BCR diversity, and presented the pan-cancer immune phenotype of IFN-γ dominant, which confers these tumors with better drug response when undergoing immune checkpoint inhibitor (ICI) treatment." (PMID 36237331, 2022). "However, there are additional disordered drivers that are altered via more complex genetic mechanisms in cancer, such as specific frameshift mutations (e.g., NOTCH1), chromosomal translocations (e.g., BCR, ERG) or copy number variations (e.g., p14ARF)." (PMID 33806614, 2021). "New strategies to target cancers driven by BCR–Abl are therefore urgently needed." (PMID 33303632, 2021). "The move to cancer-specific, targeted therapies began with BCR-ABL fusion targeting using imatinib." (PMID 34948433, 2021). "Among the 29 identified fusion partners, BCR is the most frequently observed in cancer cell lines." (PMID 33257674, 2020). "Fusion rates differ across cancer types, and fusions may define some cancer types, such as BCR--ABL1 in chronic myeloid leukemia." (PMID 32471990, 2020). "Furthermore, BCR has been uncovered as a fusion partner in 19 additional translocations found in various cancers." (PMID 31105873, 2019). "Although CAR-T therapy has been investigated in BCR-ABL driven ALL to date, it is hypothesized that this line of T cell therapy will also be beneficial in additional BCR fusion-driven cancers." (PMID 31105873, 2019). "Interestingly, BCR fusion proteins that are drivers of cancer have only been identified in hematological cancers." (PMID 31105873, 2019). "Also highlighted are the functional consequences of aberrant splice variants (BCR-Abl35INS, BIM-γ, IK6, p61 BRAF V600E, CD19-∆2, AR-V7 and PIK3CD-S) in promoting resistance to cancer targeted therapy or immunotherapy." (PMID 30463359, 2018). "Moreover, cancer cells, including BCR/ABL-positive cells, show an increased level of glucose metabolism, resulting from the shift from oxidative phosphorylation to glycolysis to supply ATP for extensive proliferation." (PMID 23965958, 2013). "Since Separase is one of the master key players in centriole duplication, and overexpression has been associated with formation of supernumerary centrosomes in cancers including CML, we investigated the influence of BCR-ABL TK on separase in the therapeutic context of IM." (PMID 22870341, 2012). "A chromosomal translocation converts Abelson kinase (ABL) to BCR-ABL, the hyperactivity of which drives several cancers." (PMID 42038481, 2026). "The dataset included variables such as cancer diagnoses, patient demographics, BCR::ABL1 biomarker data, and detailed cancer treatment information, including pharmacy records." (PMID 41542066, 2026). "The discovery of BCR::ABL and the kinase inhibitor imatinib revolutionized cancer care and research, marking the transition toward precision medicine." (PMID 38833619, 2025). "SIAIS562055 also potentiated the activity of both KRAS inhibitors in KRAS-mutant cancers and ABL inhibitors in BCR–ABL–positive CML." (PMID 39437162, 2025). "Imatinib is the first receptor tyrosine kinase (RTK) inhibitor with activity against ABL, BCR-ABL, PDGFR, and c-KIT, and is the standard of care in chronic myelogenous leukemia (CML), GIST, DFSP, and various other cancers." (PMID 40558511, 2025). "Drugs such as imatinib, trastuzumab, and gefitinib inhibit the activity of specific proteins or receptors, like BCR-ABL, HER2, and EGFR, responsible for the growth and division of cancer cells." (PMID 39685591, 2024).
cancer (continued). "Imatinib binds to the active site of BCR-ABL, halting cancer cell proliferation and restoring control over the cell cycle." (PMID 39685591, 2024). "Imatinib is an ABL kinase inhibitor targeting BCR::ABL and it was the first example of a targeted cancer therapy." (PMID 37509339, 2023). "Imatinib is a tyrosine kinase inhibitor (TKI) that specifically targets the breakpoint cluster region(BCR)-Abelson leukemia virus (ABL) fusion protein in chronic myeloid leukemia (CML) and has beenwidely used in the treatment of various cancers." (PMID 38023990, 2023). "The discovery of the Philadelphia chromosome 1 (Ph1) and BCR::ABL gene fusion sparked substantial interest in uncovering and exploring the roles of gene fusions in cancer." (PMID 37509339, 2023). "Our knowledge of how the BCR::ABL1 gene and resulting protein drive cancer cell progression and survival through complex processes within the cell which promote cell growth and switch off normal cell death pathways." (PMID 38550948, 2023). "Conversely, dasatinib has not been reported to bind to nuclear receptors but is a potent inhibitor of BCR-ABL and is a standard drug of choice for molecular targeted therapy for malignant tumors." (PMID 37762164, 2023). "The BCR-ABL TKIs inhibit ABL kinase with variable potency, leading to the use of very different doses to achieve cancer benefits, depending on the agent." (PMID 37983208, 2023). "Utilizing the patient datasets from Pan-Cancer (c-Bioportal), we observed a significant positive correlation between DDR1 expression and expression of genes BCR, EGFR, and ERBB2." (PMID 35664781, 2022). "Imatinib, a selective inhibitor of the breakpoint cluster region (BCR)-ABL kinase, is the poster child for targeted cancer therapeutics." (PMID 35252553, 2022). "Nevertheless, BCR/ABL1 inhibition with imatinib (Gleevec), a tyrosine kinase inhibitor, resulting in ceasing disease progression, was the first success of cancer targeted therapy, changing CML from a fatal disorder into a chronic disease." (PMID 33671579, 2021). "Imatinib, while being designed to target the cancer-specific BCR-ABL fusion, has been shown to also target other kinases in cancer, making it a promising treatment for use outside of cancers with the Philadelphia chromosome." (PMID 34948433, 2021). "Here, we used CRISPR/Cas9 to specifically target the BCR-ABL junction region in K562 cells, resulting in the inhibition of cancer cell growth and oncogenesis." (PMID 32485885, 2020). "For example, in cancer, GNAS, BCR and SNRPN showed both expression downregulation and CNV losses, while for HM13, gains were linked with overexpression." (PMID 30297886, 2018). "The results showed that the TCR, BCR, MAPK, insulin, and Wnt pathways as well as various cancer signaling pathways were targeted by miR-155." (PMID 27532002, 2016). "For pan-cancer ANOVA, the set of CFEs included 267 CGs, 407 RACSs, and three gene fusions (BCR-ABL, EWSR1-FLI1, and EWSR1-X)." (PMID 27397505, 2016). "This analysis shows that the 1CT7 specific mutated genes are altered in 30.4% of all CRC cases whereas A1309 specific mutated genes are altered in 73.6% of all CRC cases, among which five genes are known cancer genes, i.e. PBRM1, MYB, PRDM16, BCR and NUP214." (PMID 25923178, 2015). "Similarly, BCR and TCR richness are indicators of the immune system's capacity to recognize and respond to cancer, with altered immune infiltrates correlating with patient outcomes in BC." (PMID 40693457, 2025). "By contrast, cancer incidences in Japanese survivors of the atomic bombs showed a peak in CML within 10 years of radiation exposure, raising the possibility that BCR::ABL1 driven clonal expansion and the trajectory to CML are unlike that of adult malignancies studied so far8." (PMID 40205062, 2025).
cancer (continued). "Venetoclax has shown significant efficacy in both AML and ALL, while dasatinib (inhibiting BCR:: ABL1) and vinaclotide (inhibiting BCL-2) have a strong synergistic effect, which may effectively “starve” and “kill” cancer cells." (PMID 41366999, 2025). "Furthermore, PD-1 blockade promotes BCR signaling and activates the PI3K/AKT pathway in cancer cells." (PMID 40692791, 2025). "Within TLSs, B cells can activate T cells through antigen-specific (BCR-dependent) and nonspecific (BCR-independent) pathways, significantly influencing immune responses in cancer." (PMID 39569184, 2024). "STAT5 inhibitors have been used to abrogate the constitutive activation of STAT5 signaling in cancer, and tyrosine kinase inhibitors (TKIs) that target the upstream signaling molecules of STAT5 — such as JAK, FLT3, and BCR-ABL — have been shown to be effective in clinical settings." (PMID 36927693, 2023). "These drugs target a fusion protein called BCR-ABL, which is localized in cancer cells." (PMID 37046701, 2023). "AS yields good outcomes with no cases of BCR and/or metastatic progression and/or cancer-related deaths in selected RTRs patients affected by localised PCa." (PMID 36710292, 2023). "Specifically, the combination of avasimibe and imatinib synergistically inhibited BCR-ABL mutation- and nonmutation-dependent imatinib CML cell proliferation by targeting cancer-specific CE accumulation, MAPK and natural BCR-ABL signaling." (PMID 37653037, 2023). "However, only a few diseases like CML are addicted to single oncogene (e.g., BCR-ABL), most cancer types rely on multiple oncogenic alterations, with only partial dependency upon an individual target or pathway." (PMID 35574302, 2022). "Since the discovery of BCR-ABL, over 500 additional oncogenic fusion proteins have been identified as drivers of hematologic malignancies, emphasizing the importance of characterizing these drivers and their respective cancers." (PMID 35574218, 2022). "As the Grb2 binding site at Tyr177 in BCR is uniformly conserved among other BCR-fusion proteins, such as BCR-JAK2, BCR-PDGFRA, BCR-RET and BCR-NTRK2, our results suggest that Shp2 and Gab1 play an equally important role in cancers driven by these oncogenes as well." (PMID 35574218, 2022). "This indicates the potential for further functional work on other cancer genes in CML to direct future therapeutic targets independent of BCR::ABL1." (PMID 35158889, 2022). "CML is a rare hematopoietic stem cell disease wherein cells harbor the characteristic “Philadelphia chromosome” (Ph), resulting from a translocation between the BCR and ABL1 genes, forming the p210 or p190 isoforms of BCR-ABL1 tyrosine kinase which drive cancer cell proliferation." (PMID 35739111, 2022). "Targeted deep-sequencing analysis of the tumors at sacrifice revealed that BA-targeted xenografted tumors analyzed 6 weeks after AdV injection were composed of non-edited (94%) or partially-edited (one locus; 3% of BCR or ABL1) cancer cells." (PMID 33033246, 2020). "Consequently, cancer systems immunologists have employed targeted amplicon sequencing (typically, of cDNA derived from amplified TCR or BCR mRNA) to evaluate the BCR and TCR repertoires, providing insight into how lymphocytes respond to tumors." (PMID 32657757, 2020). "The Cancer Genome Atlas (TCGA) data analysis indicated that the gene expression of TRIO, NET1, ECT2, TIAM2, FARP1, ARHGEF12 and BCR in primary cancer was significantly higher than those in normal tissues." (PMID 32029704, 2020). "Although these therapies have only been investigated in Ph+ cancers to date, it is speculated that both CAR-T therapy and BiTE therapy will be beneficial in treating additional BCR fusion driven cancers." (PMID 31105873, 2019). "Although the reason behind the commonality of BCR as a fusion partner is not understood, we aim to discuss the mechanisms and current treatment options for cancers driven by these fusions." (PMID 31105873, 2019).